IGF1 (insulin like growth factor 1)
Diseases named in the same sentence as IGF1 in open-access papers (continued):
Sharing a sentence is not in itself a finding about the gene and the disease.
Stroke (164 papers, 2008 to 2026). Sudden impairment of blood flow to a part of the brain due to occlusion or rupture of an artery to the brain. "Decreased levels of IGF-1 have been shown to be associated with better functional outcome after stroke." (PMID 41094027, 2026). "Clinically, low circulating IGF-1 levels are correlated with an increased stroke risk, higher mortality, and poorer functional outcomes, though results can be inconsistent." (PMID 41304786, 2025). "Growth hormone (GH) deficiency following a stroke reduces insulin-like growth factor 1 (IGF-1) levels and osteoblast activity, which leads to decreased bone mass and density." (PMID 40904972, 2025). "Epidemiological studies have reported inconsistent associations between IGF-1 and stroke risk, while preclinical evidence supports its vascular and neuroprotective properties." (PMID 41586110, 2025). "Post-stroke changes in the peripheral IGF-1 level are associated with favourable stroke outcomes and improved recovery." (PMID 40141452, 2025). "Given the substantial global burden of stroke-related disability, these findings highlight IGF-1 as a possible biomarker for risk stratification during recovery phases." (PMID 41586110, 2025). "Histological studies also confirmed loss of IGF‐1 cortical neurons in children with IESS due to stroke." (PMID 40019827, 2025). "Lower IGF-1 levels post-stroke are associated with worse outcomes, increased inflammation, and a higher mortality risk." (PMID 40142325, 2025). "Recent evidence strongly supports the vital role of IGF-1 in promoting neuronal survival following ischemic cerebral damage, enhancing stroke outcomes and preventing additional neuronal loss." (PMID 41256775, 2025). "An increase in the cGP/IGF-1 ratio is associated with more favourable clinical outcomes, including improved memory retention and stroke recovery." (PMID 38921582, 2024). "Clinical trials demonstrated that low concentrations of cGP and decreased cGP/IGF-1 ratios in the plasma are associated with impaired IGF-1 function during the early stages of stroke." (PMID 38921582, 2024). "We found a U-shaped relationship between IGF-1 concentrations and the risk of dementia and stroke – both high and low IGF-1 concentrations implying a higher risk." (PMID 37608387, 2023). "There is also inconsistency in the association of IGF-1 with the risk of stroke and Parkinson's disease (PD)." (PMID 37608387, 2023). "Hypertension is a life-long risk factor for stroke and shares the pathology of endothelial dysfunction and the pathophysiology of impaired IGF-1 function." (PMID 36770687, 2023). "Considering the U-shaped associations of IGF-1 concentrations with dementia and stroke, the second quartile of IGF-1 was treated as the reference group when evaluating the associations between quartiles of IGF-1 and these outcomes." (PMID 37608387, 2023). "Decreased IGF-1 circulation levels are associated with an increased risk of stroke and a poorer prognosis, but the relationship with cerebral small vessel disease (cSVD) is unclear." (PMID 37358957, 2023). "Several clinical studies have found that patients with low circulating IGF-1 levels at admission have a higher mortality rate and are associated with increased stroke scale scores from the National Institute of Health several months after stroke." (PMID 37358957, 2023). "This association between cGP/IGF-1 ratio and stroke recovery provides additional evidence for cGP as a regulator of IGF-1 function." (PMID 36770687, 2023). "In summary, the findings from this large population-based study suggest U-shaped associations of circulating IGF-1 concentrations with the risk of dementia and stroke and a linear association with that of PD." (PMID 37608387, 2023). "Lower serum IGF-1 levels at admission are associated with a higher risk of developing post-stroke depression." (PMID 37358957, 2023).
Stroke (continued). "Our findings extend previous knowledge by identifying both high and low IGF-1 concentrations as being risk factors in the development of dementia and stroke in general population." (PMID 37608387, 2023). "An age-related deficiency in IGF-1 production and function can contribute to cardiovascular aging, as well as cerebrovascular diseases such as stroke, hypertension, and cognitive impairment." (PMID 36770687, 2023). "An inverse relationship exists between stroke risk and functional outcomes following strokes and IGF-1 and IGFBP-3 levels." (PMID 35547443, 2022). "In contrast, targeted ablation of Gal-3+ microglia/macrophages in MCAO was associated with decreased IGF-1 levels but increased apoptosis and stroke size." (PMID 34831271, 2021). "IGF-1 levels decline in advanced age, and the extent of this decline is associated with increased risk of stroke incidence, increased mortality, and worsened functional outcomes post-stroke in humans." (PMID 34887742, 2021). "The age-related reduction in circulating levels of insulin-like growth factor-1 (IGF-1) is associated with increased risk of stroke and neurodegenerative diseases in advanced age." (PMID 34887742, 2021). "Low IGF-1 levels were linked to coronary atherosclerosis and re-stenosis, ischemic heart disease, congestive heart failure, and stroke." (PMID 32655494, 2020). "It reduces the progression of atherosclerosis, and in cross-sectional studies, IGF-1 levels were inversely associated with ischemic stroke, higher serum levels of IGF-1 at the time of stroke is associated with a significant better outcome." (PMID 30361294, 2018). "Our observations from other clinical and experimental studies show that the increase of cGP and/or cGP/IGF-1 ratio is associated with weight changes in obese women, post-natal development, and spontaneous recovery in stroke patients." (PMID 29865234, 2018). "We recommend a routine screening of serum IGF-1 levels in patients having different stroke risk factors as a preventive measure." (PMID 30595648, 2018). "Lower serum IGF-1 levels are significantly related to risk of stroke, independent from other traditional and emerging risk factors." (PMID 30595648, 2018). "A recent study showed that not only low levels of IGF-1 were associated with an unfavourable functional outcome of stroke but also the level of insulin-like growth factor binding protein-3 (IGFBP-3)." (PMID 28373915, 2017). "More specifically, the subjects with low plasma IGF‐I levels have a higher risk of stroke and have a worse prognosis after stroke than those patients with high plasma IGF‐1." (PMID 28961383, 2017). "In the wake of this evidence many studies have shown the beneficial effect of IGF-1 administration after stroke, reducing neuronal loss and infarct volume, while increasing glial proliferation." (PMID 26417600, 2015). "Other studies have shown that high levels of IGF-1 before stroke are associated with a larger ischemic area." (PMID 21110846, 2010). "Furthermore, we investigated potential associations between improved post-stroke recovery and serum IGF-1 levels, as IGF-1 has been shown to be associated with post-stroke functional outcome." (PMID 41094027, 2026). "IGF-1 may serve as a potential prognostic biomarker for long-term functional decline after stroke, but causality and its therapeutic implications remain uncertain." (PMID 41586110, 2025). "However, in the subgroup analysis of IGF-1's effect on unfavorable outcomes after ischemic stroke, IGF-1 was significantly associated with poor prognosis more than 1 year after stroke onset (RR = 3.33, 95% CI = 2.19–5.05, I2 = 0%, random-effects model)." (PMID 41586110, 2025). "However, in the subgroup analysis, IGF-1 was significantly associated with poor prognosis more than 1 year after stroke onset (RR = 3.33, 95% CI = 2.19–5.05, I2 = 0%, random-effects model)." (PMID 41586110, 2025).
Stroke (continued). "However, patients with higher IGF-1 levels exhibited an increased risk of poor prognosis at >1 year post-stroke, suggesting potential relevance for long-term outcomes." (PMID 41586110, 2025). "Moreover, an earlier study that followed 757 older adults for 10 years reported that lower serum IGF-1 levels were associated with a higher incidence of stroke." (PMID 38414630, 2024). "Furthermore, lower circulating IGF-1 concentrations have been linked to unfavorable outcomes following stroke." (PMID 40789569, 2024). "Probing the IGF-1 system may, therefore, lead to a molecular biomarker-based precision medicine approach to identify patients who are both at risk of stroke and amenable to IGF-1 targeting interventions." (PMID 36979670, 2023). "It has been shown that low circulating Igf1 levels were associated with higher stroke incidence." (PMID 35557964, 2022). "Longitudinal observation-based clinical assessments have identified multiple possible biomarkers of stroke risk and severity, including insulin-like growth factor-1 (IGF-1), which may serve as a point of therapeutic intervention in the days surrounding insult." (PMID 34887742, 2021). "Hypertension was the major risk factor associated with low IGF1 in RA and stroke." (PMID 31327319, 2019). "Our laboratory has previously demonstrated that stroke severity in older females is associated with decreased IGF-1 availability and IGF-1 treatment, provided intracerebroventricularly, after stroke protects the aging brain by reducing blood brain barrier disruption and neuroinflammation." (PMID 27905989, 2016). "IGF-1 is a critical endogenous neuroprotectant and low normal levels of peptide hormone are associated with increased morbidity and mortality in ischemic heart disease and stroke." (PMID 23365789, 2013). "Insulin-like growth factor (IGF)-1 is a critical endogenous neuroprotectant and low normal levels of peptide hormone are associated with increased morbidity and mortality in ischemic heart disease and stroke." (PMID 22393433, 2012). "However, our study firstly found that a lower IGF-1 concentration was moderately associated with a higher risk of stroke and a higher IGF-1 concentration might slightly increase the risk of stroke." (PMID 37608387, 2023). "Given its association with age-related cognitive status and stroke recovery, changes in cGP/IGF-1 molar ratio and/or cGP concentration could be a better plasma biomarker to identify those at greater risk of cognitive decline and poor ability to recover from stroke." (PMID 36770687, 2023). "However, given the unique importance of mTOR signaling for skeletal muscle hypertrophy, it is plausible to suggest that stroke-induced downregulation of IGF1 and PI3K-Akt associated genes may reduce protein synthesis and contribute to skeletal muscle atrophy." (PMID 32629989, 2020). "To determine the potential association between IGF-1 and stroke recovery in our study, we quantified serum IGF-1 levels in the pre-stroke, sub-acute (at 10 days post-stroke) and endpoint phases after stroke." (PMID 41094027, 2026). "We show that HFD-fed mice treated with either vehicle (PBS) or BI8271 had significantly higher IGF-1 levels pre-stroke compared with mice fed a standard diet." (PMID 41094027, 2026). "Brains and serum were collected, and stroke volume and serum IGF-1 levels were quantified (secondary outcomes)." (PMID 41094027, 2026). "Collectively, IGF-1 plays a key role in regulating oxidative stress, inflammation, and brain repair after ischemia, reinforcing its relevance to stroke pathophysiology." (PMID 41586110, 2025). "Another study demonstrated that central injections of IGF-1 in a rat model of stroke had a protective effect on the brain–blood barrier (BBB), which prevented the development of neuroinflammation." (PMID 40801621, 2025).
Stroke (continued). "Elevating the number of insulin-like growth factor-1 (IGF-1)-expressed microglial cells following stroke can attenuate cellular apoptosis and facilitate the proliferation and differentiation of neural stem cells (NSCs)." (PMID 40556734, 2025). "Third, IGF-1 promotes angiogenesis and neurogenesis, both essential for long-term neurological restoration after stroke." (PMID 41586110, 2025). "Insulin-like growth factor-1 (IGF-1), an oxidative stress–related neurotrophic factor, has been investigated in stroke due to its potential roles in neuronal survival and vascular regulation." (PMID 41586110, 2025). "Clinically, IGF-1 measurement is feasible and inexpensive, indicating potential as a prognostic indicator for post-stroke management." (PMID 41586110, 2025). "Our aim is to achieve early identification of PSCI and post-stroke cognitive impairment with dementia (PSCID) in stroke patients through the use of the blood biomarker insulin-like growth factor-1 (IGF-1)." (PMID 39963470, 2025). "Future prospective, large-scale studies with standardized IGF-1 measurements and comprehensive adjustment for confounding factors are needed to confirm the prognostic utility of IGF-1 and clarify its biological relevance in post-stroke recovery." (PMID 41586110, 2025). "Nonetheless, given IGF-1’s important role in brain function and the high prevalence of post-stroke depression, further research should explore this relationship." (PMID 40283415, 2025). "In order to better reveal the neuroprotective effects of boosting microglial Igf1 expression on stroke outcomes, AAV‐DIO‐siTrem2 combined with AAV‐DIO‐Igf1 were simultaneously injected into Cx3cr1‐Cre+ mice brains prior to MCAO." (PMID 38151703, 2024). "Previous studies have shown that in a mouse stroke model, IGF-1 released from microspheres induces the production of new neurons in the subventricular zone (SVZ), which then migrate toward the injured striatum." (PMID 38707461, 2024). "Recent studies have demonstrated that administering IGF-1 three days post-stroke significantly improves tissue recovery and sensory-motor functions, indicating its therapeutic efficacy in stroke rehabilitation." (PMID 38377025, 2024). "Reduced IGF-1 bioavailability in patients often indicates age-related conditions such as hypertension, stroke, and neurological disorders with cognitive impairment." (PMID 38921582, 2024). "Expression of IGF1, which has been reported to provide protection after stroke by improving CBF and BBB function, is induced in reactive PDGFRβ+ pericytes upon increasing PDGF-D brain abundance." (PMID 38769116, 2024). "Treatment with IGF-1 has also been shown to promote cerebrovascular angiogenesis and increase vessel density, for example in post-stroke models and in the normal adult mouse brain." (PMID 36755922, 2023). "The following section reviews the role of cGP in regulating IGF-1 function at the onset of stroke and during first 3 months of recovery as a neurological condition of vascular origin." (PMID 36770687, 2023). "IGF-1 serum level has been found to be influenced by stroke, with a decrease in IGF-1 in acute stroke being related to a positive outcome." (PMID 37371326, 2023). "Changes in the hypothalamic-pituitary-adrenal (HPA) axis, the sympathetic nervous system, and the levels of several hormones, including natriuretic peptides, melatonin, and IGF-1, occur after a stroke." (PMID 37733793, 2023). "This prospective study included 369,711 participants (55.8 ± 8.1 years) from the UK biobank who had serum IGF-1 measured and were free from brain-related disorders of interest — dementia, stroke, and Parkinson’s disease (PD) — at enrollment (2006–2010)." (PMID 37608387, 2023). "Above 26 nmol/L, the HR of stroke per 1-SD increment of IGF-1 was 1.09 (95% CI: 1.02–1.17) in model." (PMID 37608387, 2023).
Stroke (continued). "The cGP/IGF-1 molar ratio is low in patients with age-related conditions, including hypertension, stroke, and neurological disorders with cognitive impairment." (PMID 36770687, 2023). "Post-stroke IGF-1 treatment can improve sensorimotor function in adults while it does not in aged rats, probably due to the different activation of microglial." (PMID 37358957, 2023). "Our novel finding provides a basis for in-depth clinical research on the relationship between IGF-1 concentrations and stroke, which is of great significance to stroke prevention, early diagnosis, and prognosis." (PMID 37608387, 2023). "Compared with the control participants, the plasma concentrations of IGFBP-3 and cGP were lower in stroke patients at the time of hospital admission, and the concentration of IGF-1 was similar." (PMID 36770687, 2023). "Higher serum IGF-1 levels during the rehabilitation phase of stroke correlate to better recovery of long-term function." (PMID 37358957, 2023). "As well, an after-stroke Intra-cerebroventricular injection of IGF-1 to female rats suppressed 2 to 5-fold pro and anti-inflammatory cytokines such as the pleiotropic cytokine, IL-6, IL-13, and CCL2." (PMID 35935038, 2022). "Prior to stroke, basal paracrine and endocrine Igf1 and Igfbp3 levels were unchanged, and endogenous regulation of Igf1 and Igfbp3 occurs later after stroke." (PMID 35557964, 2022). "We determined the expression levels 2 days after 45 min MCAo in Zfp580 knockout mice to determine if Zfp580 has an effect on the paracrine cerebral Igf1 and Igfbp3 regulation following stroke." (PMID 35557964, 2022). "IGF1 is involved in neurogenesis, oligodendrogenesis, and myelination, and reduces stroke-induced BBB damage and sustained antiinflammation in the brain." (PMID 35572941, 2022). "This is supported by the fact that not only intracerebroventricular administration of Igf1 improves outcome after stroke, but even systemic injections of Igf1 are effective." (PMID 35557964, 2022). "Although a series of studies have applied IGF-1 in brain insults such as stroke and TBI, the clinical application is limited due to its adverse effects found in animal studies." (PMID 36062186, 2022). "We demonstrate in this study that Zfp580 interacts via Igf1 and Igfbp3 signaling with mechanisms relevant to stroke outcome." (PMID 35557964, 2022). "For the mediator models based on the categorical weight change variable, we identified age, smoking, alcohol use, walking, COPD, stroke, estrogen use, IGF-1, 25(OH)D, albumin, height, ln-SHBG, and ln-PTH as confounders." (PMID 34272641, 2022). "Concerning stroke severity, several studies have shown that circulating Igf1 and Igfbp3 were reduced after stroke and that post-stroke Igf1 and Igfbp3 serum levels were inversely associated with infarct volume." (PMID 35557964, 2022). "Next, we evaluated the effects of stroke on Zfp580, Igf1 and Igfbp3 expression after 60 min of transient filamentous middle cerebral artery occlusion (MCAo) for short-term regulation up to 3 days in wild-type C56/BL6 mice." (PMID 35557964, 2022). "With this study, we identified Zfp580 as a novel modulator of Igf1 and Igfbp3, which differentially steers paracrine cerebral and endocrine systemic responses after stroke, leading to induced Igf1 signaling." (PMID 35557964, 2022). "In this study, we evaluated the effects of zinc finger protein 580 (Zfp580) on endocrine and paracrine Igf1 and Igfbp3 after stroke." (PMID 35557964, 2022). "In contrast, higher systemic Igf1 levels prior stroke were correlated to larger infarct size in mice." (PMID 35557964, 2022). "Insulin-like growth factor 1 (Igf1) and insulin-like growth factor binding protein 3 (Igfbp3) affect stroke occurrence and severity, as well as stroke recovery." (PMID 35557964, 2022). "Insulin-like growth factor 1 (Igf1) and insulin-like growth factor binding protein 3 (Igfbp3) are endocrine and paracrine factors that influence stroke occurrence, severity, and recovery." (PMID 35557964, 2022).